ROCK2 (Rho associated coiled-coil containing protein kinase 2)
Description:
Protein kinase which is a key regulator of actin cytoskeleton and cell polarity. Involved in regulation of smooth muscle contraction, actin cytoskeleton organization, stress fiber and focal adhesion formation, neurite retraction, cell adhesion and motility via phosphorylation of ADD1, BRCA2, CNN1, EZR, DPYSL2, EP300, MSN, MYL9/MLC2, NPM1, RDX, PPP1R12A and VIM. Phosphorylates SORL1 and IRF4. Acts as a negative regulator of VEGF-induced angiogenic endothelial cell activation. Positively regulates the activation of p42/MAPK1-p44/MAPK3 and of p90RSK/RPS6KA1 during myogenic differentiation. Plays an important role in the timely initiation of centrosome duplication. Inhibits keratinocyte terminal differentiation. May regulate closure of the eyelids and ventral body wall through organization of actomyosin bundles. Plays a critical role in the regulation of spine and synaptic properties in the hippocampus. Plays an important role in generating the circadian rhythm of the aortic myofilament Ca(2+) sensitivity and vascular contractility by modulating the myosin light chain phosphorylation.
Synonyms: ROCK-II
Tractability: Small molecule: an approved drug acts on it; a structure with a bound ligand is known; a high-quality ligand is known; it belongs to a druggable protein family. Antibody: UniProt places it where antibodies can reach, with medium confidence; its Gene Ontology location is reachable by antibodies, with medium confidence. PROTAC: ubiquitination databases record sites on it; its protein half-life has been measured; a small molecule that binds it is known.
Target class: AGC protein kinase DMPK family; Enzyme; Kinase; Protein Kinase; AGC protein kinase ROCK subfamily; AGC protein kinase group
Chemical probes: BAY-549 (high quality), LACTOQUINOMYCIN, ML014, PD082149, PD134700, PD134702
Safety:
Unwanted effects reported when the protein is acted on. In parentheses: how it was acted on, where the effect was seen, and who reports it.
Anxiety (inhibition; central nervous system; source: Brennan et al. (2024))
cardiac dysfunction (inhibition; cardiovascular; source: Brennan et al. (2024))
cytopenia (inhibition; blood/bone marrow; source: Brennan et al. (2024))
GI disorder (inhibition; gastrointestinal; source: Brennan et al. (2024))
lymphatic disorder (inhibition; lymph; source: Brennan et al. (2024))
Memory impairment (activation; central nervous system; source: Brennan et al. (2024))
nervous system disorder (activation; central nervous system; source: Brennan et al. (2024))
pulmonary hypertension (inhibition; respiratory; source: Brennan et al. (2024))
heart disease (cardiovascular system; source: Force et al. (2011))
Gene: Protein-coding gene on chromosome 2 (11,179,759 to 11,348,330, reverse strand). Ensembl gene ENSG00000134318.
Subcellular location: Cytoplasm; Cell membrane; Nucleus; Cytoplasm, cytoskeleton, microtubule organizing center, centrosome
Subcellular location (Human Protein Atlas): Cytosol
Pathways (Reactome):
Signal Transduction: G alpha (12/13) signalling events; RHO GTPases Activate ROCKs; RHOA GTPase cycle; RHOB GTPase cycle; RHOBTB1 GTPase cycle; RHOC GTPase cycle; RHOH GTPase cycle; VEGFA-VEGFR2 Pathway
Developmental Biology: EPHA-mediated growth cone collapse; EPHB-mediated forward signaling; Sema4D induced cell migration and growth-cone collapse
Disease: Potential therapeutics for SARS
Gene Ontology:
Molecular function: endopeptidase activator activity; protease binding; protein binding; protein serine/threonine kinase activity; Rho-dependent protein serine/threonine kinase activity; RNA binding; structural molecule activity; tau protein binding; tau-protein kinase activity; ATP binding; protein kinase activity; protein serine kinase activity; small GTPase binding
Biological process: centrosome duplication; host-mediated perturbation of viral process; negative regulation of angiogenesis; negative regulation of bicellular tight junction assembly; negative regulation of nitric oxide biosynthetic process; negative regulation of protein localization to lysosome; positive regulation of amyloid precursor protein catabolic process; positive regulation of amyloid-beta formation; positive regulation of cell migration; positive regulation of protein localization to early endosome; positive regulation of stress fiber assembly; protein localization to plasma membrane; protein phosphorylation; regulation of establishment of endothelial barrier; regulation of keratinocyte differentiation; Rho protein signal transduction; actin cytoskeleton organization; actomyosin structure organization; aortic valve morphogenesis; blood vessel diameter maintenance; cellular response to acetylcholine; cortical actin cytoskeleton organization; embryonic morphogenesis; epithelial to mesenchymal transition; mitotic cytokinesis; and 27 more
Cellular component: centrosome; cytoplasm; cytoplasmic ribonucleoprotein granule; cytosol; nucleus; cytoskeleton; plasma membrane
Genetic constraint (gnomAD): Loss-of-function variants: 26 observed, 104.15 expected, observed/expected ratio (o/e) 0.25, 90% interval 0.18 to 0.35. The upper end of that interval is the gene's LOEUF score, 0.35, which puts it in group 1 of 6, group 1 being the genes least tolerant of losing a copy. Missense variants: 747 observed, 1,145.1 expected, observed/expected ratio (o/e) 0.65, 90% interval 0.61 to 0.69. Synonymous variants: 352 observed, 381.66 expected, observed/expected ratio (o/e) 0.92, 90% interval 0.84 to 1.01.
Gene-disease validity (ClinGen):
ClinGen rates the evidence that ROCK2 causes each of these diseases.
congenital heart disease (autosomal dominant): Limited. A heart disease that is present at birth.
Homologues: Orthologues: chimpanzee ROCK2 (99% identical), macaque ROCK2 (99% identical), dog ROCK2 (97% identical), mouse Rock2 (97% identical), rat Rock2 (97% identical), pig ROCK2 (95% identical), guinea pig ROCK2 (93% identical), tropical clawed frog rock2 (82% identical), rabbit ROCK2 (78% identical), zebrafish rock2a (75% identical), zebrafish rock2b (63% identical), Drosophila melanogaster Rok (44% identical), and 4 more. Paralogues in human: ROCK1 (64% identical), CIT (29% identical), CDC42BPA (27% identical), CDC42BPB (26% identical), CDC42BPG (22% identical).
Diseases named in the same sentence as ROCK2 in open-access papers:
ROCK2 is named in the same sentence as 213 diseases in open-access papers, as found by Europe PMC text mining. Sharing a sentence is not in itself a finding about the gene and the disease. The quoted sentences say what the papers report.
breast cancer (35 papers, 2008 to 2025). A primary or metastatic malignant neoplasm involving the breast. "Previous research on ROCK2 gene and its relevance to breast cancer are proven and a critical amino acid mutation (T431N) is identified as the high-risk factor in breast cancer metastasis." (PMID 28477017, 2017). "A recent study demonstrated that ROCK2 gene polymorphisms are significantly associated with colorectal cancer or metastases of breast cancer." (PMID 26377148, 2016). "Indeed, ROCK2 is overexpressed and associated with increased invasion and metastasis in breast cancer and bladder cancer." (PMID 34959725, 2021). "Thr431Asn polymorphism of the ROCK2 gene could be a risk factor for the metastases of breast cancer." (PMID 26725045, 2016). "It has been reported that SNORA71A promotes breast cancer metastasis by stabilizing ROCK2 mRNA through binding with the G3BP protein." (PMID 38594783, 2024). "Analysis results from Kaplan–Meier Plotter indicate that the expression of both VAMP3 and ROCK2 predicts worse OS in breast cancer patients." (PMID 38627816, 2024). "ROCK isoforms differentially regulate the RhoA/ROCK1/p-MLC and RhoA/ROCK2/p-cofilin pathways in a coordinated fashion to modulate breast cancer cell motility in a substrate stiffness-dependent manner through integrin β1-activated FAK signaling." (PMID 37916166, 2023). "Real‐time PCR showed ROCK2 was increased in breast cancer tissues compared to normal tissues adjacent to carcinoma, and showed a significantly positive correlation with SNORA71A expression." (PMID 35100495, 2022). "After screening, source genes closely associated with canine mammary tumours were found to include RYR2, PDE4D, ROCK2, CREB3L2 and UBA3, and associated circRNAs included chr27:26618544-26687235-, chr26:8194880-8201833+ and chr17:7960861-7967766-." (PMID 35622733, 2022). "In breast cancer cells, the downregulation of ROCK2 changed the hardness of the extracellular matrix, which affects the chemosensitivity of tumor cells." (PMID 33153478, 2020). "It was reported that ROCK2 regulated the development of colorectal cancer, prostate cancer, glioma, breast cancer, and bladder cancer." (PMID 30266988, 2019). "Conversely, ROCK2 levels do not seem to vary significantly between normal and tumor tissue, although a significant decrease was seen in ROCK2 mRNA levels in patients who died from breast cancer." (PMID 26377148, 2016). "This is consistent with our previous reports where steroid hormone receptors activate G-protein–ROCK-2-Moesin signaling in breast cancer and other cell models." (PMID 27746764, 2016). "mRNA and protein expression of ROCK1, ROCK2 and RhoA are increased in the tissue of breast cancer patients; however, only the increased levels of ROCK1 and RhoA correlate with poor patient prognosis." (PMID 27203208, 2016). "In the case of ROCK2, phospho-selective antibodies against this Ser1366 post-translational modification were used to stain breast cancer clinical samples to detect ROCK2 activation." (PMID 25288205, 2014). "ER-dependent PI3K activation results in the activation of the RhoA/ROCK-2 cascade and through this manner it increases ezrin activity in breast cancer cells." (PMID 21818323, 2011). "In T47-D breast cancer cells, an enhanced interaction between ERα and ROCK-2 was found with co-immunoprecipitation experiments in cells exposed to E2." (PMID 18493596, 2008). "Pre-incubation of T47-D or MCF-7 breast cancer cells with the specific Rho-kinase inhibitor, Y-27632 (Y-27632, 10 μM) prevented the activation of moesin by estradiol, implying that ROCK-2 is required for estrogen signaling to moesin in ER+ breast cancer cells." (PMID 18493596, 2008). "The co-expression of BRCA2 and ROCK2 in breast cancer suggest the joint effect in tumorigenesis, which may guide the effect enhancement of BRCA2 inhibitors on tumor cells." (PMID 39013885, 2024).
breast cancer (continued). "Furthermore, we overexpressed SNORA71A and knockdown ROCK2 to further verify the SNORA71A controls breast cancer by ROCK2." (PMID 35100495, 2022). "Moreover, the GEPIA database showed that the expression of G3BP1 had a significant positive correlation with the expression of ROCK2 in breast cancer." (PMID 35100495, 2022). "Likewise, the same effect was seen after specific knockdown of RHOA, ROCK1 and ROCK2 by siRNA in all three ROR2-overexpressing breast cancer cell lines." (PMID 34911552, 2021). "We also found two transcription factors (ROCK2, USF3) in the distal components of the CTRL- and MAP3K6-associations with survival; both transcription factors are interconnected within the MAPK pathway, known to be involved in breast cancer proliferation." (PMID 33684137, 2021). "Furthermore, immunohistochemical (IHC) analysis of breast cancer samples with the ROCK1 and ROCK2 autophosphorylation site antibodies revealed that nuclear ROCK2 activation was associated with increased metastasis and poor patient outcomes." (PMID 30667325, 2020). "Besides, estrogen-dependent PI3K activation has also been reported to enhance cell motility and invasion by activating the RhoA/ROCK-2 cascade and ezrin activity in breast cancer cells." (PMID 26845172, 2016). "In addition, small-molecule inhibitors of ROCK2 have demonstrated efficacy in preventing invasion of breast cancer cells." (PMID 25686838, 2015). "Moreover, increasing substrate stiffness may stimulate an integrin β1-activated FAK signaling, which in turn promotes the activation of RhoA/ROCK1/p-MLC and RhoA/ROCK2/p-cofilin signaling cascades toward the motility and migration of breast cancer cells." (PMID 33562737, 2021). "In the present study, we first revealed the snoRNA expression profiles in EMT‐activated breast cancer cells and identified a snoRNA that functions as a positive regulator of EMT by upregulating ROCK2 expression in the TGF‐β signaling pathway." (PMID 35100495, 2022). "We experimentally validated the predicted miR-142-3p targets ROCK2, CFL2, RAC1, WASL, and ITGAV in St-T1b cells using qPCR, which is in accordance with our previous findings in breast cancer cells." (PMID 32824678, 2020). "These evidences support one of the SNORA71A mechanisms that it might recruit G3BP1 to the mRNA of ROCK2, thus increasing the mRNA stability of ROCK2, promoting thereby the EMT development of breast cancer by TGF‐β signaling." (PMID 35100495, 2022). "We suggest SNORA71A enhances metastasis of breast cancer by binding to G3BP1 and stabilizing ROCK2." (PMID 35100495, 2022). "A lot of research have reported that ROCK2 plays an important role in invasion and metastasis in multiple cancers and its high expression is correlated with poor prognosis in a variety of human cancers, including HCC, breast cancer and lung cancer." (PMID 30266988, 2019). "More recently, hypoxia-inducible factor (HIF) has been shown to transcriptionally up-regulate RhoA and ROCK1, not but ROCK2, in breast cancer cell lines in response to hypoxia in 2D culture." (PMID 27203208, 2016). "In breast cancer cells, BRCA2 directly binds to nucleophosmin and ROCK2 at centrosomes; the dysfunction of BRCA2, which accounts for the majority of heredity breast and ovarian cancer, causes aberrant centrosome amplification and a high frequency of multinucleated cells." (PMID 26725045, 2016). "Results showed ROCK2 was successfully overexpressed using the pcDNA 3.1 vector in MDA‐MB‐231 cells, and the ROCK2 itself could promote the migration and invasion of breast cancer cells." (PMID 35100495, 2022). "PPP1R14B interacts with ROCK2 (“IntAct” EBI-7009696), which is a key regulator of the actin cytoskeleton and cell polarity and is one of the most highly overexpressed phosphatase-related proteins in triple-negative breast cancer (TNBC), which has the worst prognosis among all breast cancers." (PMID 31652503, 2019).
hepatocellular carcinoma (31 papers, 2012 to 2026). A malignant tumor that arises from hepatocytes. "High expression of ROCK2 protein has been found to be associated with more aggressive behavior in hepatocellular carcinomas." (PMID 26377148, 2016). "Our findings suggest that targeting ROCK2-ezrin signaling is a potential therapeutic niche for celastrol-based intervention of cancer progression in hepatocellular carcinoma." (PMID 32647287, 2020). "In this study we found that the inhibitory effect on hepatoma cell migration was taken through ROCK2-ezrin pathway." (PMID 32647287, 2020). "In a line with our ezrin Thr567 phosphorylation inhibition results, celastrol inhibits the phosphorylation of ROCK2, and therefore perturbs its kinase activity in hepatocellular carcinoma cells." (PMID 32647287, 2020). "It has been reported in hepatocellular carcinoma that ROCK2 regulates the cell division process by regulation of the ubiquitination of Cdc25A, a G1/S transition protein." (PMID 31488179, 2019). "Overexpression of miR-124 inhibits aggressiveness of hepatocellular carcinoma cell by targeting ROCK2 and EZH2." (PMID 24279510, 2013). "ROCK2 was overexpressed in hepatocellular carcinoma, and down-regulation of ROCK2 can suppress cancer metastasis and progression." (PMID 22920603, 2012). "ROCK2 promotes invasion and metastasis in hepatocellular carcinoma through disturbing MKP1." (PMID 36775902, 2023). "In addition, the binding of celastrol to ROCK2 inhibits the migration of hepatocellular carcinoma, mainly through the impaired ROCK2-mediated phosphorylation of ezrin, resulting in ineffective ezrin activation." (PMID 36355541, 2022). "Furthermore, the hsa-mir-185/ROCK2 pathway was shown to have potential to improve therapies in hepatocellular carcinoma, through metastasis inhibition." (PMID 34485404, 2021). "ROCK2 promotes hepatocellular carcinoma via the ubiquitination of CDC25A." (PMID 34128694, 2021). "According to the fact that ROCK2 serves as the potential target of celastrol, we next examined whether celastrol could inhibit the ROCK2 mediated ezrin Thr567 phosphorylation in hepatocellular carcinoma cells." (PMID 32647287, 2020). "This experiment further confirmed our hypothesis, which celastrol inhibits hepatoma cell migration via ROCK2-ezrin pathway." (PMID 32647287, 2020). "For example, miR-448 inhibits invasion and EMT by downregulating ROCK2 in hepatocellular carcinoma." (PMID 29483929, 2018). "ROCK2 is overexpressed in human hepatocellular carcinoma (HCC) cells, and its inhibition induces ubiquitin-mediated degradation of Cdc25A, which is responsible for cell cycle progression through the S phase via CDK2/Cyclin-E activation." (PMID 33546351, 2021). "Together with our previous ROCK-ezrin signaling regulates the intrahepatic cancer metastasis, we identified a novel chemical drug, celastrol, which could target the ROCK2-ezrin signaling as a potential therapeutic drug to prevent the hepatocellular carcinoma metastasis." (PMID 32647287, 2020). "As ROCK2 and ezrin are compartmentalized in cells and accessibility of the celastrol to its target and dephosphorylation of pre-phosphorylated ezrin could be the time-limited factor, we then treated the hepatocellular carcinoma cells with 500 nM celastrol in time gradient." (PMID 32647287, 2020). "There are also studies confirmed that drug sensitivity increased after knockdown of ROCK2 in OC cells, and interrupting ROCK pathway can promote apoptosis in hepatocellular carcinoma cells." (PMID 30266988, 2019). "In hepatocellular carcinoma (HCC), vascular channels were formed, and these vessels were associated with RhoC FAK/Paxillin signaling regulation as well as with high expression of RhoC/ROCK2, VE-cadherin, and MMP2 mediated by ERK/MMPs signaling." (PMID 31993365, 2019). "LA14 alleviated the d-GalN-induced upregulation of ROCK2, FBLIM1, and COL12A1, which suggested that LA14 might contribute to the prevention of hepatocellular cancer during acute liver injury." (PMID 34128694, 2021).
hepatocellular carcinoma (continued). "It has been proved that ROCK2 knockout and Thr567 nonphosphorylation mutant could efficiently reduce hepatoma cell velocity." (PMID 32647287, 2020). "For example, the oncogenes ROCK2 and EZH2 that are direct targets of tumor-suppressive miR-124 in hepatocellular carcinoma, and the IQGAP1 who is directly repressed by miR-124 in HCC cell lines and plays important functions in the cell adhesion and motility." (PMID 25069957, 2014).